TRPC1 (transient receptor potential cation channel subfamily C member 1)
Diseases named in the same sentence as TRPC1 in open-access papers (continued):
Sharing a sentence is not in itself a finding about the gene and the disease.
cancer (continued). "Among them, TRPV6 is overexpressed in a number of cancer cell types and participates in the progression of prostate cancer, acquiring its oncogenic potential via Orai1/TRPC1-dependent translocation to the plasma membrane." (PMID 30223530, 2018). "The data suggest that (−)-EA achieves cancer cell cytotoxicity by inducing sustained Na+ entry through heteromeric TRPC1/TRPC4 channels and that the cytotoxic effect of (−)-EA can be potentiated by Na+/K+-ATPase inhibition." (PMID 27875305, 2017). "The involvement of TRPC1 in (−)-EA-induced cytotoxicity was therefore assessed by knockdown of endogenous TRPC1 in the cancer cell lines." (PMID 27875305, 2017). "This channel has a specific regulation in cancer, also depending on the stage of malignant transformation: the TRPC1 expression level decreases with the progression of the prostate cancer from the androgen-dependent to androgenin dependent phase." (PMID 27289382, 2016). "Formation of this complex leads to the formation of lipid-raft Cav-1/Orai1/TRPC1 complex cooperating with SK3 to promote SOCE-dependent cancer cell migration." (PMID 27102434, 2016). "The TRPC1/KCa3.1 connection has been reported as an important Ca2+ signaling mechanism in the regulation of cancer cell migration, but so far only one study has reported a link between KCa3.1 and TRP channels in cancer cell proliferation." (PMID 27183905, 2016). "The involvement of TRPC1 in cell proliferation in different types of cancers as well as in endothelial progenitor cells has been previously reported." (PMID 27981039, 2016). "In conclusion, form the data available, TRPC1 seems to be a general player involved in both cancer as well as endothelial cell migration although the molecular mechanism is still elusive." (PMID 24204345, 2013). "Beside the described role on cancer cell migration, a proangiogenic role for TRPC1 has been described in vivo." (PMID 24204345, 2013). "Targeting TRPC1, a key cancer-supporting factor, may confer enhanced selectivity to this therapeutic approach." (PMID 39594815, 2024). "The detected synergism between PEMF exposure and DOX chemotherapeutic efficacy may pave the way for the development of new clinical strategies aimed at reducing DOX dosages, especially in cancers characterized by TRPC1 overexpression." (PMID 39594815, 2024). "It is reported that TRPC1 plays a vital role in various cancers." (PMID 35548183, 2022). "Recent studies have also suggested a functional role of TRPC1 in various cancers." (PMID 36187775, 2022). "TRPC1 is a crucial MIC involved in the regulation of cancer cell migration and metastasis (Canales Coutiño and Mayor, 2021)." (PMID 36158191, 2022). "Thus, in the lung (A549) and hepatocellular (Huh7) cancer cell lines, the depletion of TRPC1 inhibits cell proliferation by decreasing the activation of AKT." (PMID 35887266, 2022). "TRPC1 regulates the migratory properties of several cancer cell types, including PDAC cell lines." (PMID 36230869, 2022). "Numerous studies have addressed the impact of TRPC1 dysregulation on hallmarks of cancer." (PMID 36230869, 2022). "This indicates that the upregulation of TRPC1 stimulates proliferation in several cancer types." (PMID 35887266, 2022). "The role of TRPC1 channels was also investigated in cancer therapy resistance." (PMID 35207698, 2022). "TRPC1 protein expression in 192 pairs of carcinoma tissue and para‐carcinoma tissue was evaluated by IHC assay; meanwhile, TRPC1 mRNA expression in 110 pairs of carcinoma tissue and para‐carcinoma tissue was evaluated by RT‐qPCR assay." (PMID 35106847, 2022). "Interestingly, some of these studies report increased TRPC1 expression after hypoxia-induced EMT via HIF-1α signaling in cancer." (PMID 34936030, 2021). "In certain cancers, TRPC1 hyperactivity may overwhelm NFAT-mediated mitochondrial homeostatic mechanisms, ultimately selecting against cancer cells with inherently high TRPC channel expression." (PMID 35141145, 2021).
cancer (continued). "Therefore, under pro-inflammatory conditions, such as those induced with the overexpression of TRPC1 or miR-146b, the proliferative capacities and chemosensitivities of certain cancers increase, whereas migratory capacities diminish." (PMID 35141145, 2021). "Elevated TRPC1 expression defines numerous types of cancers." (PMID 35141145, 2021). "Negative selection by DOX against cancer cells with elevated TRPC1 expression may contribute to the commonly described chemotherapy paradox, hallmarked surviving cancer cells with heightened chemoresistance." (PMID 35141145, 2021). "The presented combinational therapeutic strategy may hence prove more selective and safer than conventional therapies, particularly for cancers characterized by elevated TRPC1 channel expression." (PMID 35141145, 2021). "However, there is still needed to develop more specific drugs to inhibit or activate TRPC1 function, so that the efficacy of TRPC1 as a potential target for cancer treatment can be verified." (PMID 34579758, 2021). "Thus more studies are required to inform the role of TRPC1 in the context of cancer in genetically engineered mouse models." (PMID 32046188, 2020). "These tools could facilitate future studies aimed at better understanding the role of TRPC1 in cancer." (PMID 32046188, 2020). "Considering the function of TRPC1, it is feasible that quantification of membrane staining of TRPC1 may lead to increased sensitivity as a prognostic indicator in cancer." (PMID 32046188, 2020). "Finally, the development of more specific pharmacological tools for inhibiting or activating TRPC1 function are needed to fully validate TRPC1 as a potential target for the treatment of cancer." (PMID 32046188, 2020). "Taken together, TRPC1 expression appears to have a role in the migration of multiple cancer types and more studies are required to determine whether inhibition of this pathway will block metastasis of primary tumors." (PMID 32046188, 2020). "In addition, TRPC1 appears to contribute to the regulation of the epithelial-mesenchymal transition (EMT) in cancer; its inhibition suppresses TGF-β1-induced EMT96,97." (PMID 32350291, 2020). "Our present findings showing that polyamine synthesis inhibition reverses remodeling of SOCs from TRPC1/Orai1 channels characteristic of cancer cells to the classic Orai1 channels reported in normal cells suggest that channel remodeling is critical to the tumorigenic pathway induced by polyamines." (PMID 30642111, 2019). "Recently, an increase in SOCE, related to the up‐regulation of Stim1, Orai1 or TRPC1 expressions, has been observed in several different kinds of tumours 6, 24, 30, indicating SOCs are the potential therapeutic target for treatment of cancers." (PMID 27878958, 2017). "In addition to cancer cells, we also monitored the effects of seeding density on the proliferation of TRPC1-silenced A7r5 cells which has a significance in examining the vascular contractile and proliferative phenotypes in vitro." (PMID 27981039, 2016). "The role of TRPC1 in cancer progression is predominantly related to cell motility." (PMID 27289382, 2016). "Moreover, the positive correlation between TRPC1 expression and cancer progression provides a therapeutic window of opportunity; TRPC1 expression can be leveraged with magnetic field treatment in combination with DOX administration to achieve greater anti-tumor outcomes." (PMID 39594815, 2024). "Besides, accumulating evidences illustrate that TRPC1 may have an oncogenic potential, which facilitates the proliferation, invasion, and dedifferentiation in numerous carcinomas." (PMID 35106847, 2022). "Thus, TRPC1 has emerged as an important player involved both in normal and cancer cell function." (PMID 32138386, 2020).
cancer (continued). "Additionally, the expression of TRPC1 as a prognostic marker in cancer appears to be context specific as TRPC1 expression has been reported to be associated with poor clinical outcomes for certain types of cancers, while in other indications it is reported to be associated with improved outcomes." (PMID 32046188, 2020). "The present study revealed that TRPC1 expression correlated with the ability of brief magnetic exposure to enhance the uptake of the chemotherapeutic agent, doxorubicin (DOX), into cancer cells." (PMID 39594815, 2024). "TRPC1 principally regulates proliferation through the phosphoinositol-3-kinase (PI3K) and mitogen-activated protein kinase (MAPK) pathways in several cancers." (PMID 35887266, 2022). "In the following section, we provide an overview of how Piezo1/2, TRPC1, TRPC5, TRPM2, TRPM4, TRPM7, TRPV2 and TRPV4 affect cancer cell behavior." (PMID 36158191, 2022). "TRPC1 is a potential regulator of store-operated Ca2+ entry (SOCE) pathways and has shown to be a potential biomarker of different cancer types, as its dysregulation correlates with several clinical parameters, including overall survival." (PMID 35887266, 2022). "In particular, we discuss the roles of Piezo1/2, TRPC1, TRPC5, TRPM2, TRPM4, TRPM7, TRPV2, and TRPV4 in mechanosensing and cancer metastasis." (PMID 36158191, 2022). "The expression profiling of several TRP ion channels, including the TRPC1, TRPM4 TRPML1 and TRPML2 genes, has been reported to predict the clinical outcome in cancer patients." (PMID 36499683, 2022). "Besides, TRPC1 mRNA expression was higher in carcinoma tissue compared with para‐carcinoma tissue (Z = −8.438, p < 0.001) as well; meanwhile, TRPC1 mRNA expression exhibited a good capability in distinguishing carcinoma tissue from para‐carcinoma tissue (AUC: 0.839; 95% CI: 0.789–0.889)." (PMID 35106847, 2022). "In human breast ductal adenocarcinoma primary patient samples, TRPC1, TRPC6, TRPM7, and TRPM8 were reported to be overexpressed in cancer cells compared to normal adjacent tissue." (PMID 32046188, 2020). "This review will focus on the role of TRPC1 expression as a determinant of SOCE and cancer progression." (PMID 32046188, 2020). "Based on their previously well-known role in cancer and metastasis, the presence of the four ion channels (HERG/Kv11.1, TRPC1, TRPC6, and TRPV6) were screened in (BNL and 1MEA) cells using a high throughput 96-well in-cell western assay (ICW)." (PMID 31627357, 2019). "Hypoxia can be sensed by several TRP channels such as TRPM7 and TRPA1, TRPC1, TRPC6, both in cancer cells and in stromal cells." (PMID 29772843, 2018). "Among them, the intracellularly located channels that are related to cancer development and progression identified so far are TRPM8 and TRPC1." (PMID 27289382, 2016). "TRPV1, TRPC1, TRPC6, and TRPM5 are also increased in cancer tissues, but further experiments are required to study the underlying mechanisms." (PMID 27023518, 2016). "In particular, TRPC1 and TRPC6 have been involved in SOCE-mediated proliferation and cytokinesis in a number of cancer types." (PMID 25126575, 2014). "Taken together, these findings demonstrate that TRPC1 is essential for PEMF-induced DOX uptake, highlighting its value as a biomarker with which to determine the potential efficacy of magnetic field therapy for certain cancers." (PMID 39594815, 2024). "A large number of literatures have shown that TRPC1 can regulate the development of multiple cancers in calcium-dependent or nondependent forms." (PMID 39165489, 2024). "Additionally, TRPC1, TRPC5, TRPM2, TRPM4, TRPM7, TRPV2 and TRPV4 can independently induce EMT in cancer cells." (PMID 36158191, 2022). "However, some studies have shown that KD of TRPC1 decreased SOCE and thereby AKT phosphorylation in different cancer cell models." (PMID 35887266, 2022). "Gain variations were observed in the great majority of cancers for TRPV6, TRPV5, TRPA1, and TRPC1." (PMID 35831825, 2022).
cancer (continued). "Indeed, knockdown of TRPC1 expression or pharmacological inhibition of TRPC1 and/or SOCE activity decreased cytosolic Ca2+ levels and abrogated cancer cell proliferation and motility." (PMID 34936030, 2021). "In addition to TRPC1 and TRPC3, the involvement of TRPC6 in cancer cell invasion and migration has been extensively investigated." (PMID 32138386, 2020). "In this review we aim to address the role of TRPC1 as a member of the SOCE pathway in promoting the advancement of the hallmarks of cancer, and consider their potential as therapeutic targets for developing novel cancer treatments." (PMID 32046188, 2020). "In addition, we found that ODC suicide inhibitor DFMO inhibits expression of TRPC1 and STIM1 in CRC cells, thus, reversing Ca2+ channel remodeling in CRC and providing a mechanism for cancer chemoprevention by polyamine synthesis inhibition." (PMID 30642111, 2019). "In addition to SOCE channels, several TRP channels contribute to the migration of cancer cells, including TRP channels TRPC1, TRPM7, TRPM8, TRPV1, TRPV2, and TRPV6." (PMID 26496025, 2015). "Stepwise regression showed that TRPC1 was a significant variable (P<0.01), but the correlation of cancer differentiation grade to sex, age, smoking, and cancer cell type was not significant." (PMID 23840757, 2013). "In addition to expression in human tissue, TRPC1 has been shown to be upregulated in cancer cell lines compared to a corresponding non-cancerous cell line." (PMID 35887266, 2022). "However, the potential contribution of TRPC1 signaling in the non-malignant mesenchymal compartment of the tumor should not be underestimated when investigating the exact role of TRPC1 in cancer progression." (PMID 34936030, 2021). "Moreover, PEMF and DOX (20 nM) anti-cancer synergism was absent in the TRPC1-silenced cells (solid and hatched dark green), but persisted in the scramble RNA-transfected cells (solid and hatched gray)." (PMID 35141145, 2021). "Experimental evidence indicates that although TRPC1 may not represent a driver of cancer, the expression of TRPC1 contributes to the hallmarks of cancer." (PMID 32046188, 2020). "However, it seems that it depends on the cancer cell type, and whether the presence or absence of TRPC1 contributes to cell growth." (PMID 35887266, 2022).
tumor (49 papers, 2012 to 2025). "TRPC1, a calcium channel associated with cell proliferation, was upregulated in the high-risk group, suggesting its role in enhancing tumor invasiveness and therapeutic resistance." (PMID 41244925, 2025). "TRPC1 also appears to regulate the activity of the tumor-associated macrophages (TAMs) within the tumor microenvironment (TME)." (PMID 39594815, 2024). "In our study, we observed that TRPC1 expression in the tumor was associated with higher T stage and TNM stage." (PMID 35548183, 2022). "TRPC1 facilitates the Ca2+ entry in tumor cells; furthermore, Ca2+ influx is closely linked with tumor cell migration and metastasis through mediating orchestrating cytoskeletal recombination, focal adhesions, and front–rear end polarity." (PMID 35106847, 2022). "Meanwhile, both TRPC1 IHC score and TRPC1 mRNA expression in tumor were associated with higher T stage (both P = 0.02) and TNM stage (P = 0.009, P = 0.003, respectively)." (PMID 35548183, 2022). "Tumor TRPC1 protein high was linked with shortened accumulating disease‐free survival (DFS) (p = 0.009) and overall survival (OS) (p = 0.026), which were also confirmed by multivariate Cox's regression analysis (both p < 0.050)." (PMID 35754147, 2022). "Tumor TRPC1 protein high was linked with shortened accumulating DFS (P = 0.009) and OS (p = 0.026) in EC patients." (PMID 35754147, 2022). "In terms of OS, tumor TRPC1 protein high (vs. low) was independently linked with shortened OS in EC patients (HR: 8.105, p = 0.007)." (PMID 35754147, 2022). "Tumor TRPC1 protein high (vs. low) was independently associated with reduced DFS in EC patients (hazard ratio [HR]: 2.963, p = 0.017)." (PMID 35754147, 2022). "The pathophysiological importance of TRPC1 in the plasma membrane is often associated with its role in Ca2+ entry, as the Ca2+ flux has been shown to be essential for tumor progression." (PMID 35887266, 2022). "In the current study, tumor TRPC1 protein high was linked with reduced accumulating DFS and OS in EC patients; meanwhile, the TRPC1 mRNA validation and survival analysis about the data from The Human Protein Atlas (derived from TCGA) obtained similar findings." (PMID 35754147, 2022). "The loss of TRPC1 protein is a potential molecular marker for tumor cell proliferation and metastasis, which is expected to be a predictive index for the prognosis of ESCC." (PMID 33854967, 2021). "Contrary to TRPV2, TRPC1 mRNA expression does show a strong association with tumor cell specific clinicopathological characteristics, which is reflected in the results obtained using EC cells." (PMID 34936030, 2021). "In this regard, the larger SOCE observed in tumor cells and increased expression of associated molecular players as Orai1, TRPC1 and Stim1, likely allows formation of larger Ca2+ domains near mitochondria." (PMID 28903423, 2017). "Thus, our results suggest that the acidic tumor microenvironment induces the trafficking of TRPC1 to the plasma membrane, likely in association with the PI3K p85α subunit and CaM, which are proteins near the plasma membrane." (PMID 36230869, 2022). "Thus, we aimed to investigate the role of the acidic tumor microenvironment and TRPC1 in association with PI3K signaling." (PMID 36230869, 2022). "These authors also provided in vivo evidence that loss of TRPC1 function impairs tumor growth in immunocompromised mice, suggesting that pharmacological inhibition of these channels may slow tumor growth." (PMID 34458247, 2021). "Moreover, SOCE was inhibited by BTP2 and 10 μM La3+, which block SOCs contributed by Orai1 and TRPC1 in a growing number of cell types, including tumor-associated ECFCs." (PMID 29221123, 2017). "Calcium influx through TRPC1 activates voltage-gated chloride channels, initiating volume changes and highlighting the ion-powered mechanism of tumor invasion and chemotaxis." (PMID 39202716, 2024).